STAT5B (signal transducer and activator of transcription 5B)
Diseases named in the same sentence as STAT5B in open-access papers (continued):
Sharing a sentence is not in itself a finding about the gene and the disease.
tumor (continued). "STAT5B also shows high expression levels in all cases of the three tumour types, and a similar trend in the ratio of nuclear versus cytoplasmic localisation as seen for STAT3, again suggesting strong activation of STAT5B." (PMID 34680385, 2021). "Comparable to STAT3, STAT5B is also expressed by a large fraction of the tumour cells, and a high proportion of the protein is located in the nucleus." (PMID 34680385, 2021). "Overall, we conclude that STAT3 and STAT5B are expressed in practically all tumour cells of the feline EATL I, EATL II and PTCL-NOS samples examined and show a high level of activation in these cells." (PMID 34680385, 2021). "Simultaneously, Stat5a and Stat5b have been found to induce the growth of tumor cells, the progression of the cell cycle and metastasis through the deregulation of the expressions of genes related to intrinsic apoptosis." (PMID 32392733, 2020). "In NPM-ALK-driven neoplasms, silencing of STAT5B blocks and silencing of STAT5A supports the disease." (PMID 30679796, 2019). "This indicates a pronounced defect of Stat5b−/− mice in tumorigenesis, which cannot be outweighed by a decreased NK cell-mediated tumor surveillance." (PMID 30679796, 2019). "miR-134 can inhibit STAT5B, Hsp90 and Bcl2 and can further inhibit the proliferation, invasion and metastasis of tumor cells." (PMID 29552328, 2018). "Six of the nine STAT5B-mutated cases were characterized with certainty as for TCR isoform expression and comprised three γδ TCR-positive tumours, two αβ TCR-positive tumours and one case positive for both TCR isoforms." (PMID 27600764, 2016). "As well, the occurrence of activating mutations in STAT5B in T-ALL suggests that constitutive activation occurring below the level of JAK/SOCS interaction may be needed to achieve the intensity/duration of downstream signaling required to support tumor propagation." (PMID 27532210, 2016). "VEGF-A expression and thus tumor promotion is suppressed by STAT5 with STAT5B being the relevant isoform." (PMID 28149296, 2016). "The intragastric administration of MSM and subcutaneous implantation of tamoxifen tablets led to tumor growth suppression and inhibition of the Janus kinase 2 (Jak2)/signal transducer and activator of transcription 5b (STAT5b) pathway." (PMID 26084564, 2015). "The molecular validation of the in vitro analysis showed that the combination had the capacity to prevent tumor growth by regulating STAT5b-IGF-1Rβ inhibition and by inhibiting metastasis via regulation of the expression of VEGF, VEGF-R2, and the MMPs." (PMID 26084564, 2015). "The results of Neuman-Keuls' multiple comparison test regarding differences in STAT5B RQ values in the studied tumor groups classified according to pTNM staging in relation to the tumor size." (PMID 25137041, 2014). "The results of Neuman-Keuls' multiple comparison test regarding differences in STAT5B immunoexpression levels in the studied tumor groups classified according to pTNM staging in relation to the tumor size." (PMID 25137041, 2014). "The regulatory effects of MSM on tumorigenesis and tumor progression were studied by examining STAT5b/IGF-1R." (PMID 22485142, 2012). "The present study focused on Stat5a and Stat5b expression in normal and malignant cells, but it will be important in future work to include analyses of expression of Stat5a and Stat5b in stromal tumor cells." (PMID 23036105, 2012). "Based on shRNA screening for the upregulated genes in in vitro carboplatin-resistant cells, we found that simultaneous knockdown of RELA and STAT5B was most effective in sensitizing tumor cells for carboplatin treatment." (PMID 20585448, 2010). "STAT5a and STAT5b regulate the transcription of the pro-proliferative genes c-myc and cyclin D1 and the anti-apoptotic genes Bcl-xL and Pim-1, to stimulate tumor growth and survival." (PMID 19630967, 2009).
tumor (continued). "This study highlights the important role of HCC‐derived exosomal miR‐500a‐3p in intercellular communication, which may be responsible for HSC activation and tumor aggressiveness via the downstream SOCS2/JAK3/STAT5A/STAT5B regulatory loop." (PMID 39574357, 2025). "These cancer-specific patterns offer valuable insights for future research directions and potential clinical applications, suggesting that STAT5B may play particularly relevant roles in specific tumor microenvironments or molecular subtypes." (PMID 41301421, 2025). "For instance, STAT5B activation is frequently observed in hematologic malignancies, where it drives proliferation and survival, whereas its downregulation in solid tumors suggests potential tumor-suppressive functions." (PMID 41301421, 2025). "The consistent pattern of downregulation in diverse tumor types implies that STAT5B may play a fundamental role in maintaining normal cellular homeostasis, with its loss contributing to malignant transformation or progression in multiple tissue contexts." (PMID 41301421, 2025). "In hematologic cancers, where STAT5B is often considered oncogenic due to its role in cytokine signaling, our results indicate that tumor-suppressive functions may dominate in specific subtypes." (PMID 41301421, 2025). "The tumor-suppressive associations of STAT5B are especially intriguing in light of non-canonical roles of STAT proteins in epigenetic regulation." (PMID 41301421, 2025). "However, following the migration of Tem cells into the tumor microenvironment, their activation is suppressed by mediators (phospholipase C gamma 1 [PLCγ1] and signal transducer and activator of transcription 5B [STAT5B])." (PMID 38203692, 2023). "Thus, higher the expression of STAT1, STAT2, STAT3, STAT4, STAT5A, and STAT5B, the lower the tumor purity." (PMID 36968603, 2023). "Importantly, both STAT3 and STAT5 can be cell type‐ or mutational context‐dependent oncoproteins or tumor suppressors, but we conclude that all three gene products, STAT3, STAT5A, and STAT5B, are oncogenes in L‐CTCL." (PMID 36341492, 2022). "C4_CD8, which was composed of cells mainly from tumor and normal adjacent kidney tissues, was associated with high activity of TFs involved in cytokine responses such as STAT3 and STAT5B." (PMID 35668194, 2022). "Similarly, STAT5B is activated in 61.46% of total tumour cells examined, and in 61.46% of EATL I, 59.3% of EATL II and 75.08% of PTCL-NOS cases." (PMID 34680385, 2021). "Furthermore, STAT5B was shown to inhibit Vegfa expression in NK cells and hence contribute to the inhibition of angiogenesis and tumor growth." (PMID 34209508, 2021). "While the expression of STAT5B was negatively correlated with tumor grades." (PMID 34276757, 2021). "Additionally, the enhanced transcriptional activity of STAT5b by breast tumour kinase (Brk) through signal-transducing adapter protein 2 (STAP-2) mediation elevated tumour cell proliferation." (PMID 32872372, 2020). "The transcription factor STAT5b is a target for tumour therapy." (PMID 28400581, 2017). "A prodrug of Stafib-1 was shown to inhibit STAT5b with high selectivity over STAT5a in tumor cells." (PMID 25702814, 2015). "Such a drug combination may have the ability to synergize tumor suppression and Jak2/STAT5b pathway inhibition." (PMID 26084564, 2015). "As so far there is no available published data concerning association of STAT5B expression with tumor progression and prognosis in NSCLC." (PMID 25137041, 2014).
tumor (continued). "Our finding that STAT5A and STAT5B are associated with redundant roles in cell proliferation and apoptosis is in keeping with several reports showing the potential of STAT5 to function as an oncogene or a tumor suppressor in humans." (PMID 24497979, 2014). "This compound can halt tumor progression by blocking STAT5b and IGF-1R." (PMID 22485142, 2012). "We hypothesize that inhibition of STAT5b would obstruct the proliferative signal that is transmitted via these kinases resulting in decreased tumor growth." (PMID 17997837, 2007). "This apparent contradiction underscores the context-dependent nature of STAT5B biology: while bulk expression of wild-type STAT5B may reflect preserved differentiation or tumor-suppressive chromatin functions, hyperactivated or mutant STAT5B can exert potent oncogenic effects." (PMID 41301421, 2025). "Similarly, STAT5B has been found to have an ability to promote tumor growth and metastasis." (PMID 38774752, 2024). "Therefore, STAT5B correlated with immune infiltrates and may play a significant role in tumor immune escape in BRCA." (PMID 36862902, 2023). "Furthermore, we wanted to evaluate whether DVL-1 regulates target genes such as STAT5B, which has been shown to play a critical role in cancer and anti-tumor immunity." (PMID 34659647, 2021). "Interestingly, the expression of DCK was associated with the gene markers like CCR8, STAT5b, and TGFB1 of Tregs, and PD–1, CTLA–4, LAG3, TIM–3, and GZMB of exhausted T cells after adjusting tumor purity, revealing that increased expression of DCK was associated with immunosuppression in HCC." (PMID 32690026, 2020). "STAT5B mutations were identified in nine samples (60%) (single mutations in seven cases and double mutations involving the same allele in two cases) and almost exclusively associated with LOH preserving the mutated allele, suggesting that the variants predominate in the tumour tissue." (PMID 27600764, 2016). "Low tumor levels of Stat5a but not Stat5b mRNA were associated with poor prognosis." (PMID 23036105, 2012). "Therefore, STAT5b not only may function in the initiation of tumorigenesis, through its pro-proliferative and pro-survival signaling, but also may promote tumor progression by mediating migration." (PMID 19630967, 2009). "We observed significant up-regulation of IL-15 signaling genes in tumor-infiltrating NK clusters, including IL15, IL2RB, IL2RG, STAT5B, and JAK1." (PMID 40315330, 2025). "In poorly differentiated tumor samples, the expression levels of STAT3 and STAT5b were significantly increased, with STAT3 expression being particularly associated with shorter patient survival." (PMID 39290697, 2024). "Taken together, we concluded that a tumor sample with high STAT1, STAT2, STAT4, and STAT5B expression levels tended to be enriched in T cell dysfunction phenotypes, while STAT6 showed to be the opposite." (PMID 36968603, 2023). "STAT1 was up-regulated in most tumor types except for KICH, while STAT5B was down-regulated in almost all TCGA tumor samples except for CHOL." (PMID 36968603, 2023). "While all STATs interact with a larger number of oncogenes than tumour suppressors, the ratio of oncogenes to tumour suppressors is highest for STAT5A and STAT5B." (PMID 35229974, 2022). "These include the tumour suppressors, PDCD4, RB1, STK2, transcriptional regulators with reported roles in cancer, BCL9L, STAT5B and proteins that are involved in control of the cell cycle, ANAPC4, ANAPC5, RBX1." (PMID 35573784, 2022). "In the greatest number of tumors, STAT4 was correlated with tumor growth, then STAT1, STAT3, STAT6, STAT5B, STAT2, and STAT5A." (PMID 36176415, 2022).
tumor (continued). "The STAT family of transcription factors, which includes STAT1, STAT2, STAT3, STAT4, STAT5a, STAT5b, and STAT6, plays distinct roles in cell differentiation, tissue repair, and anti-tumor response." (PMID 36324680, 2022). "STAT3: Among the seven members of the STAT protein family (STAT1, STAT2, STAT3, STAT4, STAT5a, STAT5b, and STAT6), STAT3 and STAT5 are the most important factors for tumor progression." (PMID 34079469, 2021). "Most of these genes (STAT5B, CDK6, CDK2, CDKN1B, E2F8, and E2F1) showed high mRNA expression in tumor tissues compared to adjacent non-tumor tissues." (PMID 32807134, 2020). "The activation of STAT3, STAT5B, and CDKN2A promotes a state of equilibrium and has tumor suppressive activities." (PMID 30325954, 2018). "The multiple effectors of Src include the PI3K/Akt, Ras/Raf/MAPK, STAT3/STAT5B, and p130 pathways; moreover, VEGFR promotes migration of tumor cells through a Src-dependent pathway." (PMID 26504896, 2015). "In this study, we proposed that MSM suppresses tumor growth via inhibition of the STAT3 and STAT5b pathways." (PMID 22485142, 2012). "Thus, specific inhibition of STAT5b/IGF-1R could be another strategy for blocking tumor growth." (PMID 22792362, 2012). "These complementary findings emphasize that STAT5A and STAT5B, despite high sequence homology, exert non-redundant biological effects on tumor behavior and patient prognosis." (PMID 41301421, 2025). "Likewise, the differences in the expression levels of STAT2, STAT3, STAT4, STAT5A, STAT5B, and STAT6 between normal and tumor tissues were also displayed." (PMID 36968603, 2023). "The average expression values of STAT1 (p < 0.001), STAT2 (p < 0.001), STAT3 (p < 0.001), STAT4 (p < 0.001), STAT5A (p < 0.001), STAT5B (p < 0.001), and STAT6 (p < 0.001) among immune subtypes C1-C6 in all tumor types were identified to have notable differences." (PMID 36968603, 2023). "Interestingly, the close association of the DTL gene and markers of Treg cells and T cell exhaustion, such as FOXP3, CCR8, STAT5B, PD-1, CTLA4, and LAG3, was found after adjusting the correlation values for tumor purity." (PMID 35392073, 2022). "For example, upregulation of STAT5B (Y699) was found exclusively in the patient whose tumor did not respond to therapy." (PMID 35338158, 2022). "The nuclear localisation of STAT3 and STAT5B observed in EATL type I, type II and PTCL-NOS tumour cells prompted us to analyse whether this is a recurrent phenomenon." (PMID 34680385, 2021). "Compared to normal samples, although MAIT cells reduced in HCC, tumor-derived MAIT cells down-regulated genes enriched in the cytokine secretion and cytolytic effect pathways (NFKB1 and STAT5B) and up-regulated genes such as IL8, CXCL12 and HAVCR2 (TIM -3) promote tumor development." (PMID 33574818, 2020). "The model of new-born infection adds another layer of complexity as STAT5B is absent in the entire organism including immunological tumor surveillance." (PMID 30679796, 2019). "This might indicate opposing roles, namely tumor-suppressive STAT5A and oncogenic STAT5B, in NPM–ALK-driven ALCL." (PMID 31690038, 2019). "In the same tumor group, the negative correlation between STAT5B and PIAS3 expression was statistically significant." (PMID 25137041, 2014). "Consequently, we could conclude that the higher expression of STAT3, STAT4, STAT5A, STAT5B, and STAT6, the higher differentiation degree and less tumor stemness characteristics of BRCA tumor cells." (PMID 36968603, 2023).
tumor (continued). "Furthermore, three CML Supertarget genes, that is, GRB2-associated binding protein 2 (GAB2), son of sevenless homolog 1 (SOS1), and signal transducer and activator of transcription 5B (STAT5B), are the components of JAK/STAT signaling pathway critical in BCR-ABL1-positive neoplasms." (PMID 37297004, 2023). "STAT5B signaling inhibition in the TME may result in lost or weakened NK cell cytotoxic functions and enhanced NK cell proangiogenic activity, which, in turn, promote tumor growth and metastasis." (PMID 34209508, 2021). "In head and neck cancer, STAT5b, but not STAT5a, was shown to be essential for tumour growth." (PMID 32899142, 2020). "Besides its role in tumor growth and cancerogenesis, HIF-1α/STAT5b signaling could also be directly related to the epileptogenicity of the tumors, by altering the buffering and networking properties of the glial network." (PMID 30621209, 2019). "In murine models, the lack of STAT5B prolongs tumor formation in vivo." (PMID 30679796, 2019). "Additionally, STAT5B and COX-2 expression levels were significantly different between T1a+T1b and T2a+T2b tumors (P = 0.002 and P = 0.041, respectively), with higher expression of both genes in T2 tumor stage." (PMID 25137041, 2014). "On the contrary, negative correlations existed in only several tumor types, such as BLCA and STAT6, GBM and STAT5B, and SARC and STAT5B." (PMID 36968603, 2023). "Studies indicated that STAT5A, but not STAT5B, is epigenetically silenced in NPM-ALK tumors and behaves as a tumor suppressor when reactivated to suppress NPM-ALK expression." (PMID 31963765, 2020). "The negative correlation between STAT5B and PIAS3 (rho = −0.43) was also observed in T2a+T2b tumor group." (PMID 25137041, 2014). "In our recent study, we found that MSM suppresses tumor growth via inhibition of the STAT3 and STAT5b pathways, while being non-toxic to normal cell line MCF-10A." (PMID 23071812, 2012). "Additionally, statistically significant negative correlation between STAT5B and PIAS3 genes was observed in T2a+T2b tumor group (rho = −0.43, P = 0.041; Spearman's rank correlation)." (PMID 25137041, 2014).